HMGA1 (high mobility group AT-hook 1)
Diseases named in the same sentence as HMGA1 in open-access papers (continued):
Sharing a sentence is not in itself a finding about the gene and the disease.
cancer (continued). "Sex, degree of differentiation, and cancer stage did not affect HMGA1 expression." (PMID 35629376, 2022). "Moreover, our findings point to the HMGA1-NF-κB-CCL2 signaling pathway that could serve as therapeutic targets in HCC and other human cancers with aberrant HMGA1 expression." (PMID 35785026, 2022). "Although the specific role and molecular mechanisms of HMGA1 in cancer have not been fully uncovered, studies have revealed that HMGA1 overexpression induced cancer cell proliferation, migration/invasion, and contributed to drug resistance in several tumors, including GC." (PMID 35049679, 2021). "Of note, this study revealed a cancer-associated truncated version of MASTL, referred to as MASTL450 that displays catalytic activity, not on Arpp19 or ENSA, but on novel substrates, such as high mobility group protein A1 (HMGA1), which has been linked to the metastatic progression of cancer cells." (PMID 32640605, 2020). "Therefore, considering the new data regarding the oncogenic potential of the extracellular localization of HMGA1, along with other proposed functions for HMGA1, such as EMT activation and cancer stem cells (CSC) maintenance, new specific drugs targeting HMGA1 are needed." (PMID 31779212, 2019). "The HMGA1-targeting miRNAs let-7a, miR-26a, miR-16, and miR-214 were downregulated in CS of both sites in the present study, giving the impression that these cancers do not differ from other malignancies in this regard." (PMID 31217897, 2019). "For the first time we demonstrated that HMGA1 has a direct role in regulating PLAU and SERPINE transcription thus directly influencing the urokinase plasminogen activator system, which is one of the best-characterized pathways involved in the metastatic spreading of cancer cells." (PMID 28924209, 2017). "The genes MAPK3, HMGB1, HMGA1, PIK3CA, and MCL1 are genes known to stimulate cellular growth; however, contrary to what is normally reported in humans, in the present study these genes were shown to be consistently expressed at lower levels in malignant tumors." (PMID 27657059, 2016). "In conclusion, based on the results presented here, we propose a novel mechanism by which HMGA1 overexpression contributes to cancer progression activating SAC gene expression, thereby inducing chromosomal instability that eventually leads to a more advanced cancer status." (PMID 26009897, 2015). "Although additional studies are needed, our findings also suggest that HMGA1 transcriptional networks are important in reprogramming normal cells into stem-like, malignant cancer cells and that these pathways could be targeted in therapy." (PMID 23166588, 2012). "An explanation for the different response of cASCs to ectopic HMGA1 application might be that functional pathways in cancer cell lines are often not comparable to the pathways of physiological somatic cells or stem cells." (PMID 22448338, 2012). "Further studies exploring the intricate interplay between HMGA1 and FKBP1A could potentially lead to novel therapeutic strategies targeting this signaling pathway to improve the effectiveness of rapamycin-based treatments in ESCC and possibly other cancer types as well." (PMID 38725843, 2024). "The DSB impairment role for HMGA1 fits well with the oncogenic role of HMGA proteins that, by impairing the proper recovery from DNA damage, could promote the progressive accumulation of DNA lesions, which eventually could provide selective advantage to cancer cells." (PMID 27723831, 2016).
cancer (continued). "Cancer pathway analysis showed that non-haematological solid tumour pathways and malignant neoplasm formation dominate late FDIM, with dysregulation of key transcription modulators, including members of the ZNF family, HMGA1, and SOX genes." (PMID 40683913, 2025). "Further analysis using tSNE visualization confirmed that HMGA1 and PARP1 expression was significantly higher in cancer cells compared with adjacent noncancerous tissues, consistent with the IHC results." (PMID 39690136, 2024). "High-mobility group AT-hook 1 (HMGA1) and high-mobility group AT-hook 2 (HMGA2), a non-histone protein, are overexpressed in diverse cancers, where they regulate developmental genes." (PMID 35328637, 2022). "Similar to HMGA1, HMGA2 is also involved in cell cycle regulation in normal and cancer cells, and its dysregulation has been shown to alter the normal cell cycle progression, possibly leading to cell cycle arrest and apoptosis." (PMID 31963852, 2020). "Three polypeptides HMGA1a, HMGA1b (together HMGA1), and HMGA2 are high-mobility group A nuclear phosphoproteins that are highly expressed in undifferentiated and cancer cells, but that are noticeably absent in adult differentiated cells." (PMID 29853899, 2018). "Here, we report that the antifungal agent ciclopirox olamine (CPX), a potential candidate for drug repurposing in cancer treatment, is able to reprogram gastric non-CSCs into cancer stem-like cells via activation of SOX2 expression and increased expression of C-MYC, HIF-1α, KLF4, and HMGA1." (PMID 37686684, 2023). "Moreover, both HMGA1 and SUZ12/CCDC43 were highly expressed in cancer cells but not in normal gastric tissues, and their expressions were positively correlated." (PMID 34167089, 2021).
tumor (232 papers, 2000 to 2026). "This was unexpected, since global deletion of Hmga1 in the biallelic Apc-deficient model led to the greatest impact on tumor development and survival." (PMID 39895630, 2025). "Surprisingly, complete loss of Hmga1 (homozygous deficiency) from colon epithelium decreases tumor incidence similar to that of haploinsufficiency." (PMID 39895630, 2025). "Survival is prolonged further (median survival 78 days; P < 0.0001, n = 7) in mice with Hmga1 homozygous deficiency, indicating that Hmga1 gene dosage modulates tumor progression in this model." (PMID 39895630, 2025). "A particular novel finding of our study is the robust association between HMGA1 and an immune-excluded tumor microenvironment." (PMID 41463532, 2025). "This interaction is significant because CBX7 typically functions as a tumor suppressor, while HMGA1 promotes tumor progression." (PMID 40175347, 2025). "To study the potential clinical relevance of the MKI67+/HMGA1 regulatory network, we created a risk prediction model based on the major tumor cell subpopulation C2 MKI67+ TCs." (PMID 40842994, 2025). "This stabilization was associated with decreased expression of HMGA1 protein levels in the tumor, suggesting that the combined treatment was capable to downregulate HMGA1 expression and therefore the resistance to trabectedin." (PMID 38758230, 2024). "HMGA1 was found to affect cell proliferation, apoptosis, and autophagy, which were linked to tumor progression." (PMID 38600248, 2024). "HMGA1 is a structural epigenetic chromatin factor that has been associated with tumor progression and drug resistance." (PMID 38758230, 2024). "Surprisingly, disrupting FGF19 via gene silencing or the FGFR4 inhibitor BLU9931 recapitulates most phenotypes observed with HMGA1 deficiency, decreasing tumor growth and formation of a desmoplastic stroma in mouse models of PDAC." (PMID 36919699, 2023). "Previous studies demonstrated that HMGA1 was an oncogene associated with GC tumors, which was involved in tumor cell migration, invasion, and cisplatin resistance." (PMID 36760722, 2023). "HMGA1 deficiency disrupts oncogenic properties in vitro while impairing tumor inception and progression in KPC mice and subcutaneous or orthotopic models of PDAC." (PMID 36919699, 2023). "To define HMGA1 function in vivo, we assessed xenograft tumorigenesis from PDAC cell lines (E3LZ10.7 and AsPC-1), which showed that HMGA1 deficiency decreases tumor volumes." (PMID 36919699, 2023). "In summary, because of the inconsistency of these functions, the mechanism by which HMGA1 causes these functions has yet to be explored to provide effective guidance for tumour diagnosis and targeted therapy." (PMID 35864955, 2022). "HMGA1 has been recognized as an oncogene, which is frequently overexpressed and implicated in tumor initiation and progression." (PMID 35114891, 2022). "HMGA1 oncogene has been demonstrated to have a causal role in BC, its expression displays a correlation with tumor grade and promotes metastatic phenotype in TNBC." (PMID 36614035, 2022). "Among them, K-Ras mutation is mainly in the early stage of PanIN lesions, and HMGA1 occurs in the late stage, meaning that HMGA1 overexpression can promote the transformation of the premise lesion of K-Ras mutation into a tumour." (PMID 35864955, 2022). "As remarked in literature, HMGA1 dysregulation causes alterations in cell-cycle progression and cell proliferation in tumor cells." (PMID 36614035, 2022). "There is another HMGA1-involved signature been proved perform well in distinguishing HCC patients at a high risk of tumor recurrence." (PMID 36685838, 2022).
tumor (continued). "Such a correlation was not noted by Lin and Peng (2016), although in their study the presence of the HMGA1 protein in NSCLC tissue samples was associated with poor histological differentiation of the tumor." (PMID 35948739, 2022). "NPI is a clinicopathological classification system based on tumor size, histological grade, and lymph node status, and our study also showed a positive association between HMGA1 expression with NPI." (PMID 36479041, 2022). "HMGA1 plays a major role in tumours recurrence and is often associated with the prediction of poor prognosis." (PMID 35864955, 2022). "The secreted form of HMGA1 was mechanistically linked to its role in tumor invasion and metastasis since blocking the extracellular HMGA1 reduced the metastatic burden in a xenograft model of TNBC." (PMID 34572547, 2021). "A large number of in vitro studies carried out on normal and tumor cells demonstrated that HMGA1/2 dysregulation causes alterations in cell cycle progression and cell proliferation." (PMID 31963852, 2020). "Afterward, several groups have specifically linked HMGA1 to migratory and invasive phenotypes in different tumor cells." (PMID 31779212, 2019). "Nevertheless, such trends in expression—although non-significant—are in accordance with recent knowledge on the importance of HMGA1 as a “master regulator” in tumorigenesis and its association with tumor aggressiveness." (PMID 31803613, 2019). "Our results reveal that HMGA1 and HMGA2 mRNA and protein are overexpressed in ECC, but only HMGA1 expression is associated with increased histological grade and tumor size." (PMID 31096664, 2019). "Overexpression of HMGA1 is significantly associated with tumor progression and EMT in multiple cancers." (PMID 31151404, 2019). "Adjusted for the largest basal tumor diameter, tumor thickness and epithelioid cell pattern, high level expression of HMGA1 was found to be associated independently with an increased risk of distant metastasis, and with shorter UM specific survival." (PMID 23935884, 2013). "There is increasing evidence suggesting that in some tumors, nuclear expression of HMGA1 was revealed a strong correlation with tumor grade and inversely associated with survival, HMGA1 protein can be used as a marker for metastatic progression." (PMID 23935884, 2013). "We also found that knock-down of HMGA1 has profound effects on oncogenic properties associated with both tumor initiation (orthotopic tumorigenesis) and tumor progression (migration, invasion, and metastatic progression)." (PMID 23658826, 2013). "In malignant neoplasias HMGA1 expression is reported to be associated with an aggressive behaviour of tumours." (PMID 18651940, 2008). "Moreover, HMGA1 levels were positively correlated with tumor mutational burden (TMB), and microsatellite instability (MSI), and immunotherapy-related checkpoints including PD-1, CTLA-4, and TIGIT." (PMID 41463532, 2025). "Within the immune cell islands, Cd4+ and Cd8+ T cells increase in frequency in the HMGA1-deficient crypt cells, the latter of which could reflect an increase in tumor-infiltrating T lymphocytes." (PMID 39895630, 2025). "These marks also associate with HMGA1 chromatin binding in other tumor settings." (PMID 39895630, 2025). "HMGA1 not only promotes the expression of ataxia-telangiectasia mutated, a key regulator of DNA damage repair, but also acts as its downstream molecule to promote DNA damage repair and enhance the chemotherapy and radiotherapy resistance of tumor cells." (PMID 40288645, 2025). "Considering that HMGA1 was highly associated with tumor metastasis and that HMGA1 interacted with STMN1, we speculated that HMGA1 may be involved in the biological process by which STMN1 promotes NSCLC metastasis." (PMID 38385074, 2024). "Hmga1 deficiency in KPC mice impairs tumor and stroma formation." (PMID 36919699, 2023).
tumor (continued). "To determine whether the tumor-promoting effects of HMGA1 are associated with macrophage infiltration, we generated an orthotopic xenograft model by using overexpression strategies in SUN-423 cells, which present lower intrinsic HMGA1 protein expression." (PMID 35785026, 2022). "It has been reported that HMGA1 can cause high CIN in tumor cells." (PMID 35163710, 2022). "Interestingly, while HMGA1 was associated with increased tumor stage (p = 0.0011), the opposite was true for HMGA1-lnc, where expression of the lncRNA is significantly decreased in more advanced tumors (p = 0.0125)." (PMID 33505435, 2020). "Our results also demonstrate a significant upregulation of HMGA1 expression following the increase in EEC histological tumor grade as well as a positive correlation between HMGA1 expression and tumor size and an association between HMGA1 levels and depth of myometrial invasion." (PMID 31096664, 2019). "Furthermore, many studies have demonstrated an association between high HMGA1 expression and aggressive tumour biology." (PMID 29743479, 2018). "The relationship between these two prominent tumour-associated genes, HMGA1 and NOTCH1, may also have prognostic value in vivo." (PMID 29743479, 2018). "HMGA1 has been implicated in tumour development and recently, but unknown at the time our study was initiated, as a reprogramming factor." (PMID 26151932, 2015). "High levels of HMGA1 expression may be linked to high proliferation rates of tumor cells by modulating chromatin structure and gene expression through DNA binding." (PMID 23935884, 2013). "Nevertheless, mice injected with HMGA1-knockdown cells displayed significant reductions in the BLI signal in the region associated with tumour colonisation of the regional homolateral axillary lymph nodes (right), which are the primary site of metastatic dissemination." (PMID 23945276, 2013). "Meanwhile, HMGA1 increases the affinity of other transcription factors enriched on DNA for their respective recognition sequences, enhances protein-protein synergism among other transcription factors and promotes the expression of genes associated with tumor progression and metastasis." (PMID 37240870, 2023). "Additionally, a high score of the HMGA1-included risk model could predict an advanced tumor grade, TNM stage, tumor invasion, and dismal clinical outcome for HCC patients." (PMID 36685838, 2022). "Finally, higher HMGA1 mRNA expression was associated with more advanced tumour grade." (PMID 23945276, 2013). "In PDAC, the high expression levels of FGF19 and HMGA1 together define a tumor subtype characterized by an extremely poor prognosis." (PMID 41328353, 2026). "Here, we identify an epigenetic mechanism whereby HMGA1 promotes tumor progression and angiogenesis via upregulation of fibroblast growth factor-binding protein 1 (FGFBP1)." (PMID 41943828, 2026). "RNA sequencing revealed that HMGA1 regulated transcriptional networks involved in tumor progression and angiogenesis, including the FGFBP1 gene." (PMID 41943828, 2026). "HMGA1 silencing suppressed oncogenic properties in vitro and reduced tumor initiating cells in HNSCC xenograft mice." (PMID 41943828, 2026). "Crucially, HMGA1 expression correlated with an immune-excluded tumor microenvironment, characterized by suppressed stromal and immune scores." (PMID 41463532, 2025). "HMGA1 has previously been reported to affect the polarization state and recruitment of macrophages in the tumor microenvironment (TME)." (PMID 41145488, 2025). "Most existing research is highly siloed, focused on single mechanisms, pathways or tumor types, which has limited broader insight into HMGA1 as a multifunctional oncoprotein." (PMID 41463532, 2025). "HMGA1 has also been shown to enhance base excision repair through its dRP/AP site cleavage activities and promote chemoresistance of tumor cells." (PMID 40288645, 2025).